PLAC8 (placenta associated 8)
Diseases named in the same sentence as PLAC8 in open-access papers (continued):
Sharing a sentence is not in itself a finding about the gene and the disease.
tumor (34 papers, 2010 to 2025). "Cluster 3 expressed monocyte markers such as Plac8 and Ly6c2 while all other clusters highly expressed tumor associated macrophage (TAM) marker Mrc1 and Trem2." (PMID 37954069, 2023). "To date, researchers have also found that PLAC8 acts as a tumor associated gene that is involved in many cancer processes." (PMID 34627411, 2021). "In a Tgfbr2-KO-to-distant-Jak2-KO task, kNN yields flat Plac8 predictions, whereas CONCERT reconstructs high Plac8 in the tumor core and low Plac8 at the surface, recovering the ground-truth spatial pattern." (PMID 41292874, 2025). "PLAC8 has been shown in fore research to be crucial in tumor progression by regulating cell apoptosis, differentiation, and proliferation." (PMID 37885015, 2023). "Overexpression of PLAC8 stimulates cell proliferation and cancer development both in vivo and in vitro while silencing PLAC8 significantly suppresses tumor growth." (PMID 37927794, 2023). "The findings revealed that PLAC8 overexpression dramatically decreased survival when compared to the control group, with statistically significant variations in tumor volume and weight between the two groups." (PMID 35497881, 2022). "In mice, the tumor grew significantly slower, and the tumor volume was significantly smaller at 30 days after implantation in the PLAC8 knockdown group than in the control group." (PMID 35497881, 2022). "Following that, we discovered that knocking down PLAC8 dramatically reduced tumor development in mice." (PMID 35497881, 2022). "PLAC8 overexpression promotes cell proliferation and cancer in vivo and in vitro, while PLAC8 silencing significantly suppresses tumor growth." (PMID 35497881, 2022). "PLAC8 was reported as a novel highly conserved protein and functioned as an oncogene or tumour suppressor in various tumours." (PMID 34117724, 2021). "Similar to the SAMs, the TAMs in the primary tumor separated into two populations: one with high expression of Chil3, Plac8, and Ly6c2 (Chil-TAMs), and the other with high expression of C1qa, C1qb, and Trem2 (Cq-TAMs)." (PMID 33782087, 2021). "Compared with other immune cells, the macrophages in the primary tumor (i.e., TAMs) exclusively exhibited high expression of the SAMs signature genes (Chil3, Trem2, C1qa, and C1qb), whereas Plac8 and Ly6c2 were broadly expressed across cell types." (PMID 33782087, 2021). "Here, animal models further supported that PLAC8 knockdown in MCF‐7/ADMR cells suppressed tumour formation ability, and the process of autophagy was promoted in PLAC8 silencing groups." (PMID 34117724, 2021). "Results from the IHC staining of Ki67 showed decreased tumour proliferation ability in the PLAC8 knockdown groups." (PMID 34117724, 2021). "PLAC8 interacts with tumor-related genes both at the transcriptional and posttranscriptional levels, thereby playing a functional role in cancer progression." (PMID 34627411, 2021). "Patients with high levels of PLAC8 in BC tissues commonly show larger tumour sizes and higher TNM stages." (PMID 31448883, 2019). "These intriguing findings elucidated pivotal oncogenic or tumour suppressor roles for PLAC8 in cancer progression." (PMID 31448883, 2019). "Collectively, the tumour‐promoting role of PLAC8 through its regulation of the PI3k/AKT/NF‐κB signalling pathway has not been previously reported." (PMID 31448883, 2019). "Then, exogenous PLAC8 was validated to significantly promote cell proliferation and xenograft tumor formation both in vivo and in vitro." (PMID 29789534, 2018). "In vitro and in vivo assays further revealed that endogenous PLAC8 promoted cell proliferation and tumor formation." (PMID 29789534, 2018). "Elevated PLAC8 levels were positively correlated with tumor size, histological grade, and tumor node metasis (TNM) stage, and LC patients with high PLAC8 expression suffered poor outcomes." (PMID 29789534, 2018).
tumor (continued). "We demonstrated that high PLAC8 expression was positively correlated with tumor progression and predicted poor outcomes in LC patients." (PMID 29789534, 2018). "First, immunohistochemistry analysis of LC TMAs confirmed that PLAC8 expression had positive correlations with tumor size, tumor histological grade and clinical stage, and high PLAC8 expression predicted a shorter overall survival time in LC patients." (PMID 29789534, 2018). "Genes associated with tumor invasiveness and epithelial to mesenchymal transition (EMT); CTSK and PLAC8 respectively, were also identified as being upregulated in CL tumors." (PMID 28045912, 2017). "On the other hand, the expression of RBP4 and PLAC8 was increased in tumor cells from mice injected with PC3-GFP/PC3-OPG in accordance with the results from RT-PCR and cDNA microarray analysis." (PMID 23708710, 2013). "We hypothesize that upon residency within CC tissues, PLAC8+ CD8+ TRMs undergo gradual differentiation into other TRM subgroups in response to persistent stimulation by tumor-related antigens." (PMID 39014148, 2024). "FWL proteins with the PLAC8 structural domain are known to be universally present in plants, mammals, and fungi and have been found to play critical roles in regulating plant organ size, metal ion homeostasis and root tumor formation." (PMID 37511542, 2023). "Based on the pan-cancer analysis, it was observed that the expression level of PLAC8 was abnormal in most tumor tissues, which may imply its significant role in tumorigenesis." (PMID 38023190, 2023). "In addition, immune analyses showed that PLAC8 was involved in remodeling the tumor microenvironment (TME) and affecting the effect of immunotherapy in ccRCC patients." (PMID 38023190, 2023). "PLAC8 is a cysteine-rich protein that serves as a central mediator of tumor evolution in mammals." (PMID 37511542, 2023). "Based on emerging evidence, PLAC8 may be a promising stemness related marker in tumor initiation and development." (PMID 34627411, 2021). "PLAC8 has a pivotal oncogenic or tumor suppressor role in cancer progression." (PMID 33611659, 2021). "Elevated PLAC8 expression promoted cell proliferation and tumor formation." (PMID 29789534, 2018). "Results from the immunohistochemical (IHC) staining of Ki67 and immunofluorescence from the terminal deoxynucleotidyl transferase dUTP nick-end labeling (TUNEL) assay showed increased tumor proliferation and decreased apoptosis in the PLAC8-overexpressing groups." (PMID 29789534, 2018). "Both tumor suppressor and promoter roles of PLAC8 have been described in previous studies." (PMID 29789534, 2018). "CD8+ TMs expressing CCL5 and GZMA, MAIT (mucosal‐associated invariant T) cells expressing TCF7 and PLAC8, and CD4+ TNs (Naïve T cells) expressing CCR7 appeared in paratumour tissues, while CD4+ISG+ T cells expressing ISG15/20 and CD8+ TNs expressing TCF7 only appeared in tumour tissues." (PMID 36855810, 2023). "In addition, PLAC8 was observed to be closely correlated with tumour size and TNM stage." (PMID 31448883, 2019). "Placenta-specific 8 (PLAC8) or Onzin is a highly conserved cysteine-rich protein that is downregulated in HCC and acts as a tumor suppressor." (PMID 36287119, 2022). "In addition, the overexpression of PLAC8 enhanced tumour growth in vitro and in vivo, as demonstrated by the observed increase in the invasive and migration capacities and decreased apoptosis induction in tumour cells, whereas PLAC8 silencing significantly inhibited cell growth." (PMID 31448883, 2019). "The IHC staining results for Ki67, PLAC8 and cleaved caspase‐3 as well as the TUNEL assay results showed increased tumour proliferation and significantly decreased apoptosis in the PLAC8‐overexpressing groups." (PMID 31448883, 2019). "Collectively, we revealed that PLAC8 acts as an oncogene in the malignant progression of LC and a novel KLF4/PLAC8 signaling pathway that regulates tumor cell proliferation and apoptosis." (PMID 29789534, 2018).
tumor (continued). "The expression of PLAC8 in LC was transcriptionally inhibited by KLF4, an important tumor-suppressive transcriptional factor during LC progression." (PMID 29789534, 2018). "Notably, genes such as PLAC8 and the Notch ligand JAG2 were significantly upregulated, while tumor suppressors, like SMARCB1, showed marked downregulation." (PMID 41595423, 2025). "Interestingly, most deregulated genes, such as IL6, RelB, RelA, Plac8, ITGA5, CXCL12 and FN1, among other cytokines and growth factors, have been involved in tumor growth and progression." (PMID 32848147, 2020). "However, the PLAC8 levels were closely correlated with the tumor size (P = 0.0400), TNM stage (P = 0.0460), and tumor differentiation (P = 0.0298)." (PMID 29789534, 2018). "For three genes—CDC42, PLAC8, and RHOA—for which no information about the variant is available in some tumor types, comparison between different datasets or tumor entities may suggest which miR-185 version is responsible for their regulation." (PMID 36287119, 2022).
cancer (28 papers, 2010 to 2025). A tumor composed of atypical neoplastic, often pleomorphic cells that invade other tissues. "PLAC8 has been implicated in the progression of multiple cancer types, including breast, lung, prostate, and colon cancer, by inducing tumorigenesis, immune response, chemotherapy resistance." (PMID 38023190, 2023). "Here, we investigated the mechanisms underlying how PLAC8 promotes cancer progression and explored the effects of altered KLF4 expression on PLAC8 in LC cells." (PMID 29789534, 2018). "Placenta-specific 8 (PLAC8) protein also plays a pivotal role in modulating the immune response, cancer growth, and progression in TNBC." (PMID 38715072, 2024). "According to previous studies, PLAC8 is a cysteine-rich protein that plays crucial roles in cell proliferation, cell immunity, cell apoptosis, and cancer pathophysiology." (PMID 37261105, 2023). "PLAC8 has been identified in the progression of various cancers by inducing tumorigenesis, immune response, chemotherapy resistance and metastasis." (PMID 38023190, 2023). "Current studies have shown that PLAC8 promotes cancer cell proliferation in the colon, pancreas, kidney, prostate, and lung tissue, while PLAC8 overexpression inhibits cancer cell growth in the liver tissue." (PMID 35497881, 2022). "The results suggested that PLAC8 expression in lung tissue was similar (significant upregulation) to that of other cancer-related genes." (PMID 35497881, 2022). "It keeps cancer cells stem-like via modulating PLAC8 expression and activating the Wnt/β-Catenin pathway." (PMID 35497881, 2022). "Studies have shown that PLAC8 overexpression contributes to MAPK pathway activation and metastatic phenotypes and that PLAC8 plays a role in the epithelial-mesenchymal transition in different types of cancer." (PMID 34627411, 2021). "This intriguing contrast in the effects of PLAC8 on cell fate in different cellular contexts presents attractive possibilities for the development of novel therapies for cancers." (PMID 34627411, 2021). "When referred to cancer immunity, PLAC8 is found to be most intensively expressed in the FXIII-A dim subgroup and helps to define three novel subpopulations in pediatric B-cell progenitor acute lymphoblastic leukemia." (PMID 34627411, 2021). "The majority of the DEGs, e.g., SOX11, TBX21, FAM3B, FGF5, HNF1A, MYB, and PLAC8 have been reported to function as promoters or biomarkers in various cancer types." (PMID 34440579, 2021). "Multiple functions of PLAC8 have been demonstrated in the regulation of immunity, adipocyte differentiation and human cancers." (PMID 34117724, 2021). "PLAC8 can regulate the proliferation of several cancer types by affecting different targets and pathways." (PMID 33611659, 2021). "Since PLAC8 was identified 20 years ago, many studies have been performed to identify the characteristics and molecular functions of PLAC8 in cancer." (PMID 34627411, 2021). "The cysteine‐rich lysosomal protein placenta‐specific 8 (PLAC8), also called onzin, has been shown to be involved in many types of cancers, and its role is highly dependent on cellular and physiological contexts." (PMID 31448883, 2019). "PLAC8 was observed to be up‐regulated in cancer tissues compared with its expression in adjacent tissues." (PMID 31448883, 2019). "PLAC8 is a 115‐amino acid, cysteine‐rich protein, and accumulating evidence suggests that PLAC8 has vital roles in many important cellular processes and in the progression of several types of cancer." (PMID 31448883, 2019). "In the current study, we aimed to determine the expression profile and the clinicopathological and prognostic implications of PLAC8 during LC development and reveal how endogenous PLAC8 expression regulates cancer cell growth." (PMID 29789534, 2018).
cancer (continued). "All these intriguing findings elucidated a pivotal role of PLAC8 in cancer progression and development." (PMID 29789534, 2018). "PLAC8 is a specific marker of iEVTs in the human placenta and has been studied and characterized in the process of trophoblastic invasion and differentiation and as a regulator of the immunotolerance activity in placental development and cancer." (PMID 40508180, 2025). "Our results implied that PLAC8 may be a novel immunotherapy biomarker of ccRCC, which is a crucial molecule in remodeling the cancer microenvironment." (PMID 38023190, 2023). "This study showed that the expression of cyclin D1 was significantly increased after PLAC8 overexpression, suggesting that PLAC8 may also promote cancer by regulating cyclin D1." (PMID 35497881, 2022). "Taken together, these results suggest that PLAC8 may predict drug resistance in various cancer cells and be a promising therapeutic target." (PMID 34627411, 2021). "Among these, PLAC8 were found to regulate autophagy-related functions in a variety of cancers." (PMID 34440579, 2021). "In addition, we highlight the diversity of PLAC8 in different tumors and its functional output beyond cancer cell growth." (PMID 34627411, 2021). "While these findings were initially unexpected, PLAC8 is an immune-related gene and may be a targeting gene for immune reactions in cancer." (PMID 34627411, 2021). "Researchers have demonstrated that PLAC8 is related to multidrug resistance in various cancers." (PMID 34627411, 2021). "Previously research revealed that PLAC8 is involved in the progression of various cancers." (PMID 34117724, 2021). "As expected, PLAC8 regulates cell apoptosis in various cancers." (PMID 34627411, 2021). "There is mounting evidence of the potential role of PLAC8-regulated network in cancer." (PMID 34627411, 2021). "We further discuss the various molecular functions of PLAC8 in cancer in our review." (PMID 34627411, 2021). "Kaplan–Meier curves show the association between gene expression and cancer survival, data indicate that patients with high expression of ITGA5 and FN1 exhibit lower survival, while the low expression of PLAC8 is associated with shorter survival." (PMID 32848147, 2020). "An alternate hypothesis is that Plac8 may promote CD8 T cell survival after IAV infection because it has been shown to promote cancer cell survival by limiting apoptosis." (PMID 32639988, 2020). "Furthermore, we analysed the IHC staining results for the samples and showed that PLAC8 was up‐regulated in the cancer tissues compared with the adjacent tissues." (PMID 31448883, 2019). "Consistent with previous studies indicated, KLF4 inhibited the growth of many cancer cell lines, including LC cells, and we further revealed that exogenous PLAC8 protects H1299 cells from KLF4-induced apoptosis and rescues the inhibitory effect of KLF4 on cell proliferation." (PMID 29789534, 2018). "Similarly, the effects of PLAC8 on cancer progression vary depending on the tissue type in other solid cancer development." (PMID 29789534, 2018). "Compared to that in normal tissues, PLAC8 mRNA was downregulated in most human cancer." (PMID 29789534, 2018). "The accumulated data thus support the idea that HMGA2 and PLAC8 may play a central role in the malignant phenotype of a broad spectrum of cancers of diverse origins." (PMID 20618946, 2010). "Also, previous studies showed that PLAC8 may be a biomarker of epithelial mesenchymal transitions progression and cancer metastasis." (PMID 37261105, 2023). "We identified a metastasis-related cancer cell subset EP1, which was characterized with a high expression of KRT17, LAMC2, EMP1, and PLAC8." (PMID 38818308, 2024). "In colon cancer, PLAC8‐overexpressing cells exhibited increased phosphorylated ERK2, which elevated cell motility and cancer invasion." (PMID 34117724, 2021).
cancer (continued). "Plac8 is known to regulate proliferation of different cancers; however, it does not appear to affect HSCs and progenitor cells under nondiabetic conditions." (PMID 36821386, 2023). "Taken together, PLAC8 may reflect epithelial-mesenchymal related genes thus involving EMT progression and cancer metastasis." (PMID 34627411, 2021).